FBXL19 (F-box and leucine rich repeat protein 19)
Description:
Substrate-recognition component of the SCF (SKP1-CUL1-F-box protein)-type E3 ubiquitin ligase complex that plays a role in different processes including cell migration, cell proliferation or cytoskeletal reorganization. Mediates RHOA ubiquitination and degradation in a ERK2-dependent manner. Induces RAC1 and RAC3 degradation by the proteasome system and thereby regulates TGFB1-induced E-cadherin down-regulation and cell migration. Also mediates ubiquitination and degradation of IL-33-induced receptor IL1RL1 and subsequently blocks IL-33-mediated apoptosis (By similarity). Within the nucleus, binds to DNA containing unmethylated cytidine-phosphate-guanosine (CpG) dinucleotides. Recruits CDK-mediator to chromatin and targets CDK8 to promoters of silent developmental genes leading to induction of these genes during cell differentiation. In addition, plays a critical role in the recruitment of RNF20 to histone H2B leading to H2B mono-ubiquitination (By similarity).
Synonyms: FBL19; DKFZp434K0410; JHDM1C; CXXC11
Tractability: PROTAC: UniProt records ubiquitination sites on it; ubiquitination databases record sites on it; its protein half-life has been measured.
Safety:
Unwanted effects reported when the protein is acted on. In parentheses: how it was acted on, where the effect was seen, and who reports it.
paradoxical psoriasiform reactions (source: ClinPGx)
Gene: Protein-coding gene on chromosome 16 (30,923,055 to 30,948,783, forward strand). Ensembl gene ENSG00000099364.
Subcellular location: Cytoplasm; Nucleus
Subcellular location (Human Protein Atlas): Nucleoplasm
Pathways (Reactome):
Immune System: Antigen processing: Ubiquitination & Proteasome degradation
Metabolism of proteins: Neddylation
Gene Ontology:
Molecular function: protein binding; ubiquitin-like ligase-substrate adaptor activity; unmethylated CpG binding; zinc ion binding; histone demethylase activity; transcription coregulator activity; DNA binding
Biological process: proteasome-mediated ubiquitin-dependent protein catabolic process; chromatin remodeling; regulation of transcription by RNA polymerase II; SCF-dependent proteasomal ubiquitin-dependent protein catabolic process
Cellular component: cytoplasm; nucleus; SCF ubiquitin ligase complex; cytosol
Genetic constraint (gnomAD): Loss-of-function variants: 16 observed, 44.88 expected, observed/expected ratio (o/e) 0.36, 90% interval 0.24 to 0.54. The synonymous counts are far from expectation, so gnomAD's model fits this gene poorly and the ratio says little. Missense variants: 658 observed, 782.38 expected, observed/expected ratio (o/e) 0.84, 90% interval 0.79 to 0.9. Synonymous variants: 447 observed, 354.51 expected, observed/expected ratio (o/e) 1.26, 90% interval 1.17 to 1.36.
Homologues: Orthologues: chimpanzee FBXL19 (100% identical), macaque FBXL19 (100% identical), dog FBXL19 (99% identical), pig FBXL19 (99% identical), guinea pig FBXL19 (99% identical), rat Fbxl19 (98% identical), mouse Fbxl19 (97% identical), rabbit FBXL19 (82% identical), zebrafish zgc:158376 (42% identical), zebrafish si:ch73-173p19.1 (12% identical), Drosophila melanogaster Skp2 (11% identical), Drosophila melanogaster Fbxl7 (11% identical), and 31 more. Paralogues in human: FBXL13 (12% identical), FBXL17 (12% identical), FBXL7 (11% identical), SKP2 (11% identical), FBXL20 (11% identical), FBXL16 (11% identical), FBXL5 (11% identical), FBXL2 (10% identical), FBXL18 (10% identical), FBXL4 (10% identical), FBXL6 (9% identical), FBXL15 (9% identical), and 3 more.
Diseases named in the same sentence as FBXL19 in open-access papers:
FBXL19 is named in the same sentence as 16 diseases in open-access papers, as found by Europe PMC text mining. Sharing a sentence is not in itself a finding about the gene and the disease. The quoted sentences say what the papers report.
psoriasis (12 papers, 2012 to 2025). An autoimmune condition characterized by red, well-delineated plaques with silvery scales that are usually on the extensor surfaces and scalp. "Patients carrying the FBXL19 rs10782001-GG genotype have been shown to be at a higher risk of developing paradoxical psoriasis when treated with anti-TNF drugs." (PMID 38898675, 2024). "This is the first study highlighting a positive association between Streptococcus skin colonization and psoriasis severity in patients with heterozygous genotypes within the FBXL19 gene region." (PMID 38898675, 2024). "The FBXL19-related SNPs rs12924903, rs10782001, and rs12445568 have all previously been linked to psoriasis, for which the risk allele is A, G, and C, respectively." (PMID 38898675, 2024). "Patients carrying the FBXL19 rs10782001-GG genotype showed a higher risk of developing paradoxical psoriasis during treatment (OR = 32.85, CI95% = 1.46–738.37, p = 0.0028)." (PMID 33921427, 2021). "The FBXL19 rs10782001 (G > A, C) polymorphism was evaluated in a study of predictive biomarkers for the risk of developing toxicity and/or paradoxical psoriasis due to anti-TNF drugs in Spanish patients with moderate-to-severe psoriasis (n = 161)." (PMID 33921427, 2021). "For some loci, this is a stronger effect size (TRAF3IP2, REL, FBXL19); for others, different genetic variants at the same locus predispose to psoriasis and PsA (IL23R) whereas other loci appear specifically associated with PsA (HLA B27, 5q31 locus)." (PMID 26255310, 2016). "Through multivariate linear regression analysis, a positive correlation was found between Streptococcus genus abundance and psoriasis severity in patients with certain FBXL19 gene-related heterozygous SNPs (rs12924903, rs10782001, rs12445568)." (PMID 38898675, 2024). "Certain SNPs in genes like IL23R, FBXL19, CTLA4, SLC12A8, TAP1, and others predispose individuals to paradoxical psoriasis." (PMID 39000125, 2024). "A previous study from our laboratory found five SNPs (rs11209026 in IL23R, rs10782001 in FBXL19, rs3087243 in CTLA4, rs651630 in SLC12A8, and rs1800453 in TAP1) associated with anti-TNF-induced paradoxical psoriasis reactions." (PMID 36143237, 2022). "Few proposed: IL23R (an allele that is protective concerning classical psoriasis), and FBXL19, CTLA4, SCL12A8, TAPl which have an unclear role in paradoxical psoriasis and the outcome of the allele is undetermined." (PMID 30555460, 2018). "Therefore, alterations of the FBXL19 gene may influence the response to biologics indicated in moderate-to-severe psoriasis." (PMID 33921427, 2021). "rs10782001 in FBXL19, rs1975974 in C17orf51, rs12720356 in TYK2, rs3792876 in SLC22A4, rs6908425 in CDKAL1, and rs13437088 in HLA-B/MICA have previously been associated with psoriasis, but not with type I psoriasis." (PMID 26613086, 2015).
glioma (3 papers, 2020 to 2022). A benign or malignant brain and spinal cord tumor that arises from glial cells (astrocytes, oligodendrocytes, ependymal cells). "For example, SNHG10 exerted oncogenic functions in glioma by sponging miR-532-3p and enhancing FBXL19 expression." (PMID 34676212, 2021). "On the contrary, FBXL19 mRNA and protein expressions were both elevated in glioma cells facing the transfection with pcDNA3.1/SNHG10." (PMID 33298070, 2020). "SNHG10 was transcriptionally activated by ETS1 and played an oncogenic role in glioma by sponging miR-532-3p and up-regulating FBXL19." (PMID 33298070, 2020). "Conclusively, ETS1 acted as a transcription activator of SNHG10 and exhibited oncogenic properties via SNHG10/miR-532-3p/FBXL19 axis in glioma." (PMID 33298070, 2020). "Such phenomenon was also certified by our present work, and we further proved that ETS1 exerted its promotion on glioma development by targeting SNHG10/miR-532-3p/FBXL19 signaling." (PMID 33298070, 2020). "Our study found that SNHG10 was an oncogene in glioma and it accelerated the malignant phenotypes of glioma cells by targeting miR-532-3p/FBXL19 axis." (PMID 33298070, 2020). "More importantly, ETS1 promoted the transcription of SNHG10 and it mediated contribution to the malignant behaviors of glioma cells by SNHG10/miR-532-3p/FBXL19 signaling." (PMID 33298070, 2020). "Moreover, SNHG10 facilitates malignant behaviors and stemness of glioma cells by targeting the miR-532-3p/F-box and leucine rich repeat protein 19 (FBXL19) axis." (PMID 35149697, 2022). "Furthermore, we designed and conducted rescue assays to validate the regulatory role of SNHG10/miR-532-3p/FBXL19 axis in glioma." (PMID 33298070, 2020). "However, present work still lacks clinical supports and in-depth animal studies to further validate the importance of SNHG10/miR-532-3p/FBXL19 axis in glioma, and these two aspects will be further focused on in our future research." (PMID 33298070, 2020). "Finally, seen from the results of wound healing and transwell assays, we knew that the hampered migration and invasion of glioma cells with ETS1 deficiency was recovered after further overexpressing SNHG10, inhibiting miR-532-3p or up-regulating FBXL19." (PMID 33298070, 2020). "In a word, SNHG10 depended on FBXL19 to accelerate the malignant behaviors of glioma cells." (PMID 33298070, 2020). "Then, we analyzed the effect of FBXL19 on the development of glioma." (PMID 33298070, 2020). "As a result, ETS1/SNHG10/miR-532-3p/FBXL19 axis was discovered, which might provide a helpful theoretic basis for the exploration of new targets for glioma therapy." (PMID 33298070, 2020). "In brief, FBXL19 was the downstream target of miR-532-3p in glioma." (PMID 33298070, 2020). "Our study found that FBXL19 was up-regulated in glioma cells, and down-regulating FBXL19 could restrict the growth and stemness of glioma cells." (PMID 33298070, 2020). "Thereafter, we uncovered FBXL19 as the downstream target of miR-532-3p in glioma." (PMID 33298070, 2020). "Also, the downstream mechanism whereby FBXL19 works as a tumor-contributor in glioma, and whether SNHG10 functions in glioma through other pathways, need to be further uncovered in future studies." (PMID 33298070, 2020). "In conclusion, FBXL19 knockdown could inhibit the development of glioma." (PMID 33298070, 2020). "Through conducting caspase 3/8/9 activity detection and TUNEL assay, we certified the facilitative effect of ETS1 knockdown on glioma cell apoptosis, while such impact was then rescued by SNHG10 up-regulation, miR-532-3p repression or FBXL19 overexpression." (PMID 33298070, 2020). "Further, we probed the function of ETS1 in glioma and whether its regulatory role was mediated by SNHG10/miR-532-3p/FBXL19 pathway." (PMID 33298070, 2020).
glioma (continued). "Furthermore, it was found that FBXL19 targeted by miR-532-3p facilitated cell growth and stemness in glioma, and that SNHG10 worked in glioma by increasing FBXL19 expression through sequestering miR-532-3p." (PMID 33298070, 2020). "Although the precise downstream mechanism of FBXL19 in facilitating glioma development was not elucidated here, it functions as a ubiquitin E3 ligase to affect the ubiquitination and degradation of certain proteins has been disclosed by several reports." (PMID 33298070, 2020). "As detected by TUNEL assays, the apoptosis of glioma cells was promoted due to the absence of FBXL19." (PMID 33298070, 2020).
Obesity (3 papers, 2021 to 2023). Accumulation of substantial excess body fat. "High-fat-diet-induced obesity is attenuated in transgenic mice overexpressing miR-26, and miR-26 at least partially blocked adipogenesis by inhibiting F-Box and leucine-rich repeat protein 19 (Fbxl19) expression." (PMID 37373175, 2023). "Still, in mice, miR-26 suppresses adipocyte progenitor differentiation and fat production by targeting Fbxl19, revealing a novel pathway in adipose tissue formation and a new potential therapeutic target for obesity." (PMID 34281170, 2021).
esophageal cancer (2 papers, 2014 to 2023). A primary or metastatic malignant neoplasm involving the esophagus. "Over-expression of FBXL19 attenuated TGFβ1-induced E-cadherin down-regulation and esophageal cancer cells elongation phenotype." (PMID 24684802, 2014). "Here we investigate the role of FBXL19-mediated Rac3 degradation in TGFβ1-induced E-cadherin down-regulation in esophageal cancer cells." (PMID 24684802, 2014). "Further, we demonstrate that FBXL19 negatively regulates Rac3-mediated TGFβ1 signaling in esophageal cancer." (PMID 24684802, 2014). "Future studies will be conducted to investigate the expression of Rac3 and FBXL19 in esophageal cancer tissues and adjacent normal tissues." (PMID 24684802, 2014). "This is the first evidence to support that Rac3 plays a critical role in the tumorgenesis of esophageal cancer and that FBXL19 exhibits an anti-tumor property by down-regulation of small GTPase." (PMID 24684802, 2014). "Inhibition of Rac3 by FBXL19 modulates E-cadherin expression in esophageal cancer cells." (PMID 24684802, 2014). "This study discovered that Rac3 plays an important role in the progress of esophageal cancer cells and the FBXL19 may function as a tumor suppressor through its ability to reduce Rac3 levels and inhibits TGFβ1 pathway." (PMID 24684802, 2014).
pneumonia (2 papers, 2016 to 2023). An acute, acute and chronic, or chronic inflammation focally or diffusely affecting the lung parenchyma, caused by an infection in one or both of the lungs (by bacteria, viruses, fungi, or mycoplasma.). "Collectively, our findings and a plethora of evidence made it plausible that FBXL19 overexpression mitigates Spn-induced lung injury in pneumonia immature mice." (PMID 36964598, 2023). "Overall, FOXM1 overexpression counteracted the protective role of FBXL19 overexpression in lung injury in pneumonia immature mice." (PMID 36964598, 2023). "We have observed similar function of other E3 ligase proteins such as Fbxl19 in acute lung injury and pneumonia." (PMID 27805901, 2016). "Furthermore, overexpression of FOXM1 reversed the protective role of FBXL19 overexpression against lung injury in pneumonia immature mice." (PMID 36964598, 2023). "Overall, FBXL19 overexpression attenuated Spn-induced lung injury in pneumonia immature mice." (PMID 36964598, 2023). "In summary, our study for the first time demonstrated the protective role of FBXL19 in Spn-induced pneumonia immature mice via ubiquitination and degradation of FOXM1, which provides a theoretical reference for the clinical study of FBXL19 in pediatric pneumonia." (PMID 36964598, 2023). "But the role of FBXL19 in Spn-induced pneumonia remains unknown." (PMID 36964598, 2023). "In light of the currently available literatures, we speculated that FBXL19 plays a regulatory role in lung injury in Spn-induced pneumonia immature mice via FOXM1, and aimed to confirm the role and downstream mechanism of FBXL19 in Spn-induced pneumonia immature mice in this study." (PMID 36964598, 2023). "However, it is unclear whether FBXL19 mediates FOXM1 ubiquitination and further plays a role in Spn-induced pneumonia." (PMID 36964598, 2023). "However, our study only confirmed a single molecular mechanism of FBXL19 in Spn-induced pneumonia immature mice, lacking exploration of the mechanism of FBXL19 and FOXM1 downregulation." (PMID 36964598, 2023). "Herein, we uncovered FBXL19 and FOXM1 as regulators of lung injury in Spn-induced pneumonia immature mice and validated a mechanism wherein FBXL19 bound to FOXM1 and induced the ubiquitination and degradation of FOXM1, thus attenuating lung injury in Spn-induced pneumonia immature mice." (PMID 36964598, 2023). "However, there is no relevant study on the role of FBXL19 in Spn-induced pneumonia." (PMID 36964598, 2023).
brain cancer (1 paper, 2023). A primary or metastatic malignant neoplasm affecting the brain. "This is a gene-rich region and we also identified GWS gene associations at this locus with FBXL19, BCL7C and CTF1, all three genes being reasonable candidates with putative roles in neuronal development, neuronal degeneration and/or brain cancer." (PMID 36940203, 2023).
breast tumor (1 paper, 2023). "In this work, we found that the expression of FBXL19 gene was higher in breast tumor tissue than in normal tissue in the TCGA database, and low expressions of FBXL19 was significantly correlated with longed over survival time." (PMID 36747547, 2023). "We obtained 5 prognosis-related genes, as the key biomarkers by Lasso-cox analysis (FBXL19, HAGHL, PHKG2, PKMYT1, and TXNDC17), all of which were significantly upregulated in breast tumors." (PMID 36747547, 2023).
periodontitis (1 paper, 2025). An acute or chronic inflammatory process that affects the tissues that surround and support the teeth. "Therefore, targeted activation of FBXL19 may represent a potentially efficacious approach for preventing bone resorption in periodontitis." (PMID 39626954, 2025). "E3s, including Cullin3 (CUL3), Nedd4‐2, Synoviolin, FBXL19, PDLIM2, TRIMs and TRAFs have been identified as key players in modulating periodontitis." (PMID 39626954, 2025). "Increasing evidence indicated that E3s, such as CUL3, Nedd4‐2, Synoviolin, FBXL19, PDLIM2, TRIMs and TRAFs, modulate inflammatory responses and bone resorption in periodontitis through multiple classical signalling pathways, including NLRP3, GSDMD, NF‐κB, Wnt/β‐catenin and Nrf2." (PMID 39626954, 2025).
rheumatoid arthritis (1 paper, 2023). A chronic, systemic autoimmune disorder characterized by inflammation in the synovial membranes and articular surfaces. "What’s more, FBXL19 is involved in inflammatory responses in rheumatoid arthritis." (PMID 36964598, 2023). "Likewise, FBXL19 is one of the hub genes in rheumatoid arthritis that exert anti-inflammatory functions." (PMID 36964598, 2023).
tumor (4 papers, 2014 to 2023). "Apart from the four genes, other genes such as FBXL19, CSTF2, ZC3H11A, CRTC1 and MAGI3 influenced the formation and progression of human cancers with either carcinogenic or tumor-suppressive function." (PMID 30640723, 2019).
cancer (2 papers, 2018 to 2019). A tumor composed of atypical neoplastic, often pleomorphic cells that invade other tissues. "In agreement with our observations, a large-scale proteomics screen previously suggested that an interaction between FBXL19 and Mediator may also exist in cancer cells." (PMID 29809150, 2018).
infection (2 papers, 2017 to 2023). The state of being infected such as from the introduction of a foreign agent such as serum, vaccine, antigenic substance or organism. "Six UPS factors were discovered to be essential for infection with the three viruses (DCAF12L, DDB1, FBXL19, OTUD6A, PAN2, and PHC2)." (PMID 29202037, 2017).
FBXL19 also shares sentences with these, for which no sentence is quoted: breast carcinoma (1 paper); cardiovascular disease (1); colorectal cancer (1); glioblastoma (1).